TNF (tumor necrosis factor)
Diseases named in the same sentence as TNF in open-access papers (continued):
Sharing a sentence is not in itself a finding about the gene and the disease.
Cachexia (continued). "Moreover, TNF/IFN‐induced cachexia in C2C12 myotubes was reported to be reduced by unacylated ghrelin in a PI3K/ mammalian target of rapamycin (mTOR)‐dependent manner." (PMID 37661635, 2023). "For example, platelet activating factor (PAF), interleukin-6 (IL-6), or tumor necrosis factor-a (TNF-α) can increase muscle breakdown and reduce protein synthesis, while in cachexia and sarcopenia, the inflammatory burden is increased, implying a bi-directional relationship." (PMID 37630805, 2023). "Studies investigating pathways involved in the onset of cachexia found several cytokines, such as TNFα, IL-1, IL-6 and LIF, which might play an important role as biomarkers or targets for tailored treatment." (PMID 36078078, 2022). "This cytokine, TNF-α, was first blamed for these changes in cachexia." (PMID 35159388, 2022). "Study has found that chronic inflammation mediated by TNF and IL-6 may promote the occurrence of cachexia in patients with GC." (PMID 36081564, 2022). "Growing evidence suggests that TME plays an important role in cancer progression and tumor‐induced cachexia by producing a variety of cachexia factors, such as macrophages, neutrophils, and fibroblasts that can produce IL‐6, TNF‐α, and other cachexia factors aggravate cachexia TME." (PMID 36105371, 2022). "The authors concluded that the presence of the CC genotype of TNF-α could be an objective biomarker of cachexia in HNC patients." (PMID 35884467, 2022). "During cachexia, there is also activation of proinflammatory cytokines such as tumor necrosis factor-alpha (TNF-α), interleukin-6 and interleukin-1, which may promote the wasting process." (PMID 35326490, 2022). "TNFα, or “cachectin”, is a proinflammatory cytokine able to induce cachexia in mice per se." (PMID 36078078, 2022). "Indeed, the administration of Rb1 for 23 days in a cancer-induced cachexia mouse model led to diminished TNF-α and IL-6 levels in serum evoked by cancer." (PMID 36139563, 2022). "This weight loss may be related to the inflammatory process, especially the presence of circulating proinflammatory cytokines such as TNF-α and IFN-γ, which may be associated with cachexia in experimental models." (PMID 35069009, 2022). "Elevated TNFα expression is also evident in several animal models of cachexia." (PMID 36077789, 2022). "Notably, there are only few data concerning the role of TNF-α −1031T/C SNP (rs1799964) in the regulation of systemic inflammatory response; however, the latest studies have demonstrated the role of this SNP as cachexia-related genetic alteration." (PMID 34900737, 2021). "Cytokines such as IL-6, TNF-α and IL-1β trigger inflammatory cascades which may play a role in the pathogenesis of chronic kidney disease (CKD)-associated cachexia." (PMID 34302016, 2021). "However, inflammatory cytokines associated with cachexia, including tumor necrosis factor (TNF), interleukin (IL)-6, IL-1β, and interferon (IFN)-γ, are unlikely to be considered potential biomarkers associated with cachexia." (PMID 33731895, 2021). "Studies have shown that cachexia patients have higher serum TNF-α and IL-6 levels." (PMID 34867338, 2021). "In the last ten years, several molecules have been proposed as biomarkers of cachexia including pro-inflammatory cytokines (e.g., interleukine 6, IL-6 and tumor necrosis factor alpha, TNF-α), hormones (e.g., leptin and ghrelin) and peptides such as C-terminal agrin fragment (CAF)." (PMID 34445710, 2021). "Indeed, we found that cachexia‐mediated induction of IL‐6 and TNF‐α, two key pro‐cachectic factors, was dampened by iNOS inhibition, despite not affecting alterations in macrophage levels, macrophage polarization, spleen swelling, and tumor size." (PMID 34096686, 2021). "In this study, we tested our hypothesis that HICA would attenuate the myotube atrophy that accompanies a decrease of protein synthesis using an in vitro cachexia model evoked by a co-exposure to TNFα and IFNγ." (PMID 34371902, 2021).
Cachexia (continued). "The reduction in body weight loss in infected mice treated with P2X7 inhibitor may result from the lower production of TNF-α by lung leukocytes, as this cytokine was originally identified by its ability to induce cachexia." (PMID 34026666, 2021). "Inhibition of these pro‐cachectic cytokines, such as IL‐6 and TNF‐α, was not effective in treating cachexia and caused unwanted side effects in these patients." (PMID 34096686, 2021). "Furthermore, cohort studies mainly indicate TNF-α and IL-6 levels as cachexia markers (reviewed in:)." (PMID 33557173, 2021). "In our mouse cachexia model, TNFα and HMGB1 in ascites and serum were increased." (PMID 33110478, 2020). "While this study implies a causal contribution of TNF-α in skeletal muscle atrophy, this may result from indirect effects of TNF-α by increasing other cytokines such as IL-6 that contribute to cachexia development by impacting on skeletal muscle." (PMID 33329046, 2020). "In a model for cachexia, Reid and Li suggested a synergistic interaction between reactive species of oxygen and nitrogen and pro-inflammatory cytokines, such as TNF-α, perhaps indicating a pathologic positive feedback loop that reduces the regulation of damaged muscle tissue repair." (PMID 32294698, 2020). "Interleukin (IL)-6, tumor necrosis factor (TNF)-α, and transforming growth factor (TGF)-β are also closely associated with several cancer-related symptoms and adverse events of anti-cancer therapy, such as cachexia and fatigue." (PMID 33050250, 2020). "The investigation was focused on the changes in the levels of TNF-α and IL-6 in mouse serum and changes in the body weights and gastrocnemius muscle weights of cancer cachexia mice to investigate whether ginseng is helpful for treating cancer cachexia." (PMID 32020864, 2020). "Intraperitoneally injected matrine (50 mg/kg for 5 or 11 days from the onset of cachexia) in C26-bearing mice lowered serum levels of TNFα and IL-6 and preserved body and gastrocnemius muscle weights, downregulating the expression of atrogenes in skeletal muscle." (PMID 33255345, 2020). "cTNT release may be under the control of pro-inflammatory cytokines, such as IL-6 and TNFα (both involved in C26-related cachexia), as also suggested by studies on how pharmacological blockade of these cytokines affects cTNT levels." (PMID 32824440, 2020). "This gene may lead to reduced production of TNF and impact disease progression and clinical symptoms associated with CWD (i.e., wasting syndrome)." (PMID 31788200, 2019). "Chronic exposure to TNF can lead to shock‐like symptoms including a wasting syndrome." (PMID 31788200, 2019). "In animal cachexia models, both plasma IL-6 and TNF-α were significantly increased." (PMID 31788012, 2019). "Of note, UCP3, a mitochondrial protein that has been shown to accumulate in cancer-induced cachexia, is under the transcriptional control of Tumor Necrosis Factor alpha (TNFα) and certain pro-inflammatory cytokines seem to be highly pro-autophagic/pro-mitophagic in cachectic environments." (PMID 31121959, 2019). "Known factors involved in cachexia, IL-1α, IL-1β, IL-6, IL-8 and TNFα are all proteins that may be produced by the innate immune cells or other non-immune cell types such as epithelial cells or stromal cells." (PMID 30513792, 2018). "This might have resulted in the release of TNF-α into circulation and eventually contributed to systemic indicators of TB, such as fever and cachexia." (PMID 30583589, 2018). "The difficulty in alleviating cachexia by using monotherapies against pro-inflammatory humoral factors such as TNFα and IL-6 has been attributed to the redundancy of downstream effectors of these cytokines and the presence of multiple signaling pathways sufficient to induce atrophy." (PMID 29849089, 2018).
Cachexia (continued). "TNF-like weak inducer of apoptosis (TWEAK), with its cognate receptor FN14 have also been implicated in muscle wasting and have been considered candidate targets for therapeutic intervention, although drugs targeting TNF-α have had limited success in cachexia human trials." (PMID 30081609, 2018). "TNFα levels were also enhanced in cachexia (p < 0.02), but only compared with the control group." (PMID 28288584, 2017). "In a model to explain cachexia, Reid and Li 17 suggested that the interaction between ROS and proinflammatory cytokines such as TNF-α are synergistic, perhaps indicative of a pathological positive feedback cycle, which is lower in the regulation of repairing damaged muscle tissue." (PMID 28355359, 2017). "Several pro-inflammatory factors, such as TNFα, IL-1β and IL-6 are up-regulated by in the adipose tissue during cachexia, and we have shown before, that the subcutaneous depot presents a relevant contribution to systemic inflammation as these factors reach the circulation." (PMID 28288584, 2017). "TNF-α's role in muscle wasting during cachexia has been well studied." (PMID 28785374, 2017). "The pro-inflammatory cytokine TNF has been well-established to play a critical role in the regulatory networks that govern IBD activity in humans, as well as to decrease appetite and enhance development of cachexia (weight loss and wasting)." (PMID 27045690, 2016). "In humans, several studies also found correlations of TNF-α serum levels with cachexia." (PMID 26856534, 2016). "It has been well-documented that a wide variety of cytokines can induce cachexia after prolonged production via multiple mechanisms, and these cytokines include TNF-α, IL-6, leukemia inhibitory factor (LIF), ciliary neurotrophic factor (CNTF) and interferon-γ (IFN-γ)." (PMID 26064446, 2015). "AH-130 ascites is known to induce cachexia mainly via elevation of plasma TNF-α." (PMID 26451159, 2015). "In addition to direct loss of contractile protein, several of the molecules that signal elevated proteolysis in cancer cachexia, such as TNF-α and NF-κB, have been shown to have depressive effects on muscle contractility." (PMID 24400146, 2013). "Expression of tumour necrosis factor-α (TNF-α, ‘cachexin’) is an important component of the human antimycobacterial immune response, but is also thought to be responsible in part for TB-related cachexia." (PMID 24086690, 2013). "In addition, many of the molecules that signal muscle wasting in cachexia, such as nuclear factor of kappa B, TNF-α, and reactive oxygen intermediates, have acute and/or persistent detrimental effects on cellular mechanisms of muscle contraction." (PMID 24400146, 2013). "They found that patients with cachexia had consistently higher levels of TNFα mRNA and protein." (PMID 21832306, 2011). "This demonstrated that TNFα was necessary for the development of cachexia in this model." (PMID 21832306, 2011). "In addition, inhibition of lipoprotein lipase by high TNF-α circulating levels can occur, decreasing adipose tissue content which may also contribute to the wasting syndrome." (PMID 38845818, 2024). "Patients with cachexia in HF are known to have dysregulated neurohormonal signaling compared to non-cachectic patients, including shifts to circulating levels of aldosterone, norepinephrine, epinephrine, cortisol, tumor necrosis factor (TNF), and human growth hormone (GH)." (PMID 38455513, 2024). "Thus, several phase 2 trials combining anti-TNF and chemotherapy have been conducted to see if blocking TNF-alpha could improve cancer-induced cachexia." (PMID 36831424, 2023). "Various pro-inflammatory factors such as TNF-α and IL-6 have been implicated in cancer cachexia, but the circulating levels of those factors do not differ significantly between PC patients with and without cachexia." (PMID 37280516, 2023).
Cachexia (continued). "However, blockade of IL-1R in mouse models was not sufficient to reverse weight loss presumably for the same reasons that anti-TNF-α monoclonal antibodies also failed to reverse the cachexia phenotype." (PMID 35743911, 2022). "In a muscle stem cell model, as well as in models of cachexia induced by human kidney neoplasia in mice, researchers observed that the process of muscle atrophy was preceded by an increase in FA β-oxidation as well as inflammatory factors, such as IL-1 β, IL-6, IL-8, and TNF-α." (PMID 36072935, 2022). "It is noteworthy that, similar to TNFα, targeting IL-6 alone may not be sufficient to treat or reverse skeletal muscle loss in cachexia." (PMID 36077789, 2022). "Interestingly, generation of TNF-α by peripheral blood mononuclear cells (PBMC) is increased in patients with chronic heart failure (CHF), especially when accompanied by cachexia, and this effect can be reversed by captopril up to 74% reduction of TNF-α synthesis." (PMID 35163696, 2022). "Increased plasma levels of fatty acids, TNF-α, IL-1, IL-6, glycerol, and lipid-mobilizing factors (zinc-2 glycoprotein-1) support the idea that increased triacylglycerol (TG) degradation may contribute decisively to cachexia." (PMID 35159388, 2022). "In addition, pro-inflammatory cytokines, such as TNF-α, IL-1, and IL-6, produced in the tumor micro-environment may have also affected cachexia in the group that experienced recurrence." (PMID 34362219, 2021). "Renewed interest in the roles of 11β-HSD1 in inflammatory muscle wasting and cachexia have been fueled by observations that its expression and GC activation are potently upregulated in peripheral tissues such as muscle in response to pro-inflammatory factors such as IL-1β and TNF-α." (PMID 33329046, 2020). "However, ablation of individual cell subsets such as CD4+ T cells or macrophages, or of TNF-α did not prevent a wasting phenotype associated with cachexia." (PMID 32676079, 2020). "In addition, this protection of weight loss occurred during the acute phases of infection and was only transient in nature, suggesting early administration of anti-TNF therapies may be more effective in the early phases of cachexia." (PMID 33329046, 2020). "Because TNF-α and possibly other cytokines contributed to cachexia following i.v. injection of iC9-CD19.ζ-MC-modified T cells, we sought to determine if the selection of CD8+ T cells (or depletion of CD4+ cells) could lessen the toxicity while preserving antitumor activity." (PMID 30816327, 2019). "However, the serum results of cancer cachexia patients were controversial, and that inhibiting TNF-α in cancer cachexia patients with weight loss did not halt the process of muscle loss in patients." (PMID 31788012, 2019). "However, serum TNF-α was positively associated with serum FFA in the early- but not late-stage cachexia." (PMID 29338749, 2018). "Furthermore, high levels of TNFα can also result in cachexia and endotoxin-induced septic shock." (PMID 29725328, 2018). "Interestingly, serum concentration of TNF-α was increased in only late-stage cachexia." (PMID 29338749, 2018). "However, serum TNF-α was positively associated with only serum FFA in early- but not late-stage cachexia." (PMID 29338749, 2018). "Additionally, TNF-α, IL-6, and other inflammatory factors lead to anorexia, the activation of skeletal muscle protein degradation, and the inhibition of protein synthesis; the following systemic inflammatory response aggravates cachexia." (PMID 28489606, 2017). "This might suggest that local injection of low-dose recombinant murine TNF (rmTNF) is not likely to cause weight loss (i.e., cachexia/wasting syndrome)." (PMID 24664144, 2014). "Thus, it would seem reasonable that higher systemic levels of CRP, TNF-α, IL-1ß, and IL-6 could be contributing factors to cachexia also in COPD patients." (PMID 22708547, 2012).
Cachexia (continued). "Inhibition of IL-6 production in this cachexia model is established to prevent the development of cachexia as shown after treatment with a murine antibody to IL-6, whereas TNF-α is thought to play an important role in wasting of fat and to induce IL-6 secretion by many cell types." (PMID 19018259, 2008). "Both the MAC16 tumour and TNF-alpha produced hypoglycaemia and a reduction in the circulatory level of free fatty acids (FFA), but had opposite effects on the level of plasma triglycerides with the MAC16 tumour-induced cachexia causing a decrease and TNF-alpha producing an increase." (PMID 3390373, 1988). "Traditional inflammatory markers including C-reactive protein (CRP), tumor necrosis factor-alpha (TNF-α), and interleukin-6 (IL-6) remain valuable indicators of the systemic inflammation driving muscle wasting, particularly in cachexia." (PMID 41220691, 2025). "Furthermore, there is scientific evidence that COPD patients who lose weight may exhibit increased TNF release from circulating cells, which may be due to TNF inducing skeletal muscle apoptosis, resulting in the distinctive cachexia seen in certain patients with severe COPD." (PMID 40136649, 2025). "In animal models, the intrahypothalamic concentration of TNFα and IL1 is increased as a consequence of the systemic inflammation that characterises cachexia." (PMID 39962362, 2025). "In both humans and mice with cancer, cachexia correlates with elevated markers of chronic inflammation, including C-reactive protein (CRP) and cytokines such as tumor necrosis factor-alpha (TNF-α), interleukin-1 (IL-1), and IL-619." (PMID 41278737, 2025). "They found that sophocarpine exerted the most potent inhibitory effect on TNF-α and IL-6 production in both RAW264.7 cells and murine primary macrophages and had a better therapeutic effect on attenuating cachexia symptoms." (PMID 38746009, 2024). "Albumin, NLR, Hb, PLR, SII, TNFα, IL-8, and CRP were reliable indicators of QoL, appetite, and cachexia." (PMID 38744744, 2024). "Elevated levels of pro-inflammatory cytokines, including tumor necrosis factor-alpha (TNF-α), interleukin-6 (IL-6), and interleukin-1 (IL-1), play a pivotal role in wasting syndrome." (PMID 38845818, 2024). "The measurement of their blood concentrations in our mouse cachexia model revealed increased IL6, TNFα, and HMGB1 concentrations in the CD group." (PMID 39125651, 2024). "An important phenomenon accompanying cachexia is the inflammatory process, during which the secretion of proinflammatory cytokines is observed, including IL-1β, Il-6, IL8, TNF-α, and interferon-gamma (INF-γ)." (PMID 38610941, 2024). "In the investigation of relationships of QoL to biomarkers of cachexia, the results showed that albumin, NLR, Hb, PLR, SII, TNFα, IL-8, and CRP were all significantly related to QL-G, QL-FS, and QL-SS aspects of QoL assessment." (PMID 38744744, 2024). "NLR, PLR, SII, TNFα, IL-6, IL-8, and CRP correlated positively to cachexia and albumin while Hb and lymphocyte count correlated negatively to cachexia." (PMID 38744744, 2024). "In line with this, CAC mice displayed markedly elevated serum levels of inflammatory factors, including IL-1, IL-6, TNF-α, TGF-β, IFN-γ, and the cachexia serum marker TLR-4." (PMID 37759730, 2023). "Cytokines that have been shown to impact on nutritional status in cachexia include C-reactive protein (CRP), tumour necrosis factor α (TNFα), interleukin (IL)-6 and IL-8 by triggering muscle wasting and negatively impacting survival in cancer." (PMID 37906352, 2023). "Moreover, this may be a fully controlled response providing, for instance, in the counteraction of tumor-induced cachexia, the inhibition of catabolic pathways (IL-6, TNF-alpha) balanced with the stimulation of anabolic pathways (FoxO3a, p-AKT, p-mTOR, and P-GSK-3β)." (PMID 38004420, 2023).